MTOR (mechanistic target of rapamycin kinase)
Diseases named in the same sentence as MTOR in open-access papers (continued):
Sharing a sentence is not in itself a finding about the gene and the disease.
tumor (continued). "Furthermore, tumour burden was significantly reduced following rapamycin treatment, confirming the role of mTOR in driving HNSCC." (PMID 30970654, 2019). "At the same time, NKG2D receptor expression on tumor cells binding to NKG2DL expressed by adjacent tumor cells leads to autostimulation of the PI3K/AKT/mammalian target of rapamycin (mTOR) oncogenic signaling pathway, promotes tumor angiogenesis and metastasis, and enhances tumor proliferation." (PMID 30813924, 2019). "In cancer cells, it usually acts as a tumor suppressor by downregulating the mTOR pathway activity." (PMID 30881383, 2019). "Therefore, the inhibition of mTOR signaling is expected to make tumor cells sensitive to radiation-induced ROS via KEAP1-NRF2 pathway attenuation, except for in the continuously hypoxic regions in the tumor tissues." (PMID 31929797, 2019). "Nuclear factor (NF)-κB, phosphoinositide 3-kinase (PI3K), extracellular signal-regulated kinase-1 and -2 (ERK1/2), Janus kinase/signal transducer and activator of transcription (JAK/STAT), and mammalian targets of rapamycin (mTOR) are shown to be involved in PD-L1 expression in tumor cells." (PMID 31817534, 2019). "Here, we demonstrate potent anti-tumor effects after dual PI3K/mTOR inhibition that may be mediated, at least in part, by disrupting nuclear GLI1." (PMID 31492956, 2019). "The mTOR signalling pathway is physiologically upregulated in different cellular mechanisms and can be aberrantly activated in human pathologies and in particular in tumours." (PMID 30795552, 2019). "Furthermore, we analyzed the protein expression of STAT3 and mTOR in 12 pairs of CRC tumor and matched adjacent normal tissues by western blot analysis." (PMID 31287013, 2019). "Interestingly, another gene that belongs to the P13K/mTor pathway involved in inhibiting P13K, namely PTEN, was identified as a periodically mutated tumor suppressor, which confirms previous studies on the recurrent mutation of MEN1." (PMID 31527438, 2019). "A 3% leucine-rich diet treatment improved muscle protein turnover by modifying the mTOR and proteolytic pathways, thus we analysed whether maternal supplementation could ameliorate muscle protein turnover in adult offspring tumour-bearing rats." (PMID 31200474, 2019). "In brief, our present findings revealed that the tumor-induced immunosuppressive molecule, PD-L1, was downregulated by Salmonella via the AKT/mTOR/p70s6K pathway, stimulated Th1 related cytokine secretion, and reactivated effector T cells, achieving significant tumor suppression." (PMID 31878272, 2019). "The Akt/ mTOR pathway might be an important player for the tumor development and a good target for drugs in patients." (PMID 30897085, 2019). "This suggests that combined inhibition of the androgen receptor and PI3K/Akt/mTOR pathways may result in measurable decline of tumor cell viability and more durable clinical benefit." (PMID 31227862, 2019). "Moreover, loss of tumor suppressors, such as PTEN, are involved in hyperactivation of the PI3K/mTOR pathway." (PMID 29351204, 2018). "As described in the previous paragraphs, the pathological changes underlying AML rupture is the rapid growth vascularization of the lesion site, and the mTOR plays the central role in the biochemical process of tumor growth and vascularization by acting as a kinase." (PMID 29668633, 2018). "In our following study, we will explore if other AKT involved signaling pathway like c-Met/Akt/mTOR pathway may be related to the synergistic anti-tumor effects." (PMID 30538636, 2018). "It is clear that exercise can ameliorate the BC microenvironment and can be very important in reducing BC risk and tumor burden when canonical radiochemotherapies or chemical mTOR inhibitors are not working, as in TNBC." (PMID 30363988, 2018).
tumor (continued). "In addition, the enzyme mTOR functions as a serine/threonine protein kinase that regulates cell growth, proliferation, motility, survival, protein synthesis, autophagy as well as cell cycle progression, and mTOR pathway activation leads to tumor development." (PMID 29633504, 2018). "For example, the synergistic effect of targeting mTOR with a combination of everolimus and another new-generation phosphatidylinositol 3-kinase/mTOR adenosine triphosphate-site competitive inhibitor BEZ235 or with the ULK1 inhibitor suppresses proliferation of tumor cells." (PMID 29643976, 2018). "It is possible that the EAC tumor might suppress the activity of mTOR in heart, which could contribute to the hyperactivation of TFEB and FoxO3a, resulting in increased proteolysis by autophagy and proteasome degradation." (PMID 29618792, 2018). "Physiological adaptations to exercise occur primarily in skeletal muscle, but the effects of exercise and training also impact other tissues through systemic control of energy homeostasis and metabolism, thus influencing the TNBC tumor microenvironment and mTOR inhibition." (PMID 30363988, 2018). "In parallel, Ubtor depletion promotes tumor growth and mTOR signaling in xenograft-bearing mice." (PMID 30080879, 2018). "Phosphatase and tensin homolog (PTEN) is a tumor suppressor which inhibits mTOR pathway." (PMID 29385181, 2018). "Together, our results indicated that HLSC-EVs and TKIs have a synergistic anti-tumor effect on renal CSCs inducing an enhancement of apoptosis by a combined effect on Akt/mTOR, Erk and Creb intracellular pathways, known to be pivotal in the induction of tumor growth and survival." (PMID 30546834, 2018). "Indeed, the blockage of mTOR with rapamycin and rapalogs reduces tumor angiogenesis by inhibiting ECs functions and VEGF secretion." (PMID 29755672, 2018). "Other studies have demonstrated that the mTOR inhibitor everolimus may sensitize tumor cells to apoptosis via p21 inhibition and inhibit cell proliferation following DNA damage." (PMID 29518028, 2018). "MPS seems to be more active than other drugs in accelerating carcinogenesis, while mTOR inhibitors might be a safer alternative given its intrinsic anti-tumor properties." (PMID 29915171, 2018). "Phd2 deletion activates the AKT–mammalian target of rapamycin (mTOR) signaling axis in tumor cells." (PMID 30575721, 2018). "We found that mTOR is highly expressed in DIPG tumour tissue." (PMID 29484131, 2018). "However, combination therapy using dual inhibitors of the MAPK and PI3K/AKT/mTOR pathways will be more effective for inhibiting proliferation and differentiation of tumor cells." (PMID 29514603, 2018). "Moreover, high lactate levels in the tumor area have been shown to suppress the PI3K/Akt/mTOR pathway inhibiting glycolysis, finally leading to impaired T cells." (PMID 29434587, 2018). "In addition to general tumor characteristics, we investigated specific treatment effects on the mTOR pathway by evaluating p-mTOR and pS6RP in all lung tumors (magnification: 400×)." (PMID 30087612, 2018). "Importantly, one study demonstrated that treatment with the mTOR inhibitor rapamycin decreases cell proliferation in vitro and delayed tumor growth in vivo using a xenograft model." (PMID 29872503, 2018). "We previously reported that long-term androgen ablation activated PI3K/Akt/mTOR signaling pathway, which explained in part the aggressiveness of CRPC, and that inhibition of PI3K/Akt/mTOR pathway showed anti-tumor effects on docetaxel resistant CRPC in vivo and in vitro." (PMID 29963230, 2018). "mTOR activation favors HIFα activity and promotes tumor angiogenesis." (PMID 29434587, 2018).
tumor (continued). "However, Caino and Altieri recently pointed to the close correlation between mTOR signaling and the crawling velocity of tumor cells." (PMID 30200497, 2018). "We found that AZD5363 drastically inhibited E2-enhanced expression of p-4Ebp1, p-mTor, and p-Gsk3β, and that of Vim and p-Fra1, suggesting that AZD5363 efficiently suppresses estrogen-enhanced Akt pathway and EMT program in Brca1 deficient tumor cells." (PMID 29996906, 2018). "Our western blotting analysis showed phosphorylation of mTOR was reduced in TB mice hearts, suggesting that EAC tumor might promote autophagy and lysosomal biogenesis through suppression of mTOR signaling in heart." (PMID 29618792, 2018). "Moreover, the combination of sorafenib and everolimus, an inhibitor of mammalian target of rapamycin (mTOR), enhanced antiproliferative, proapoptotic and antiangiogenic effects, reducing tumor growth and its propensity to metastasize in OS mice model." (PMID 29520051, 2018). "UBTOR depletion promotes tumor growth and mTOR signaling in xenograft-bearing mice." (PMID 30080879, 2018). "Current studies have shown that CEP55 promotes tumor progression via PI3K/AKT/mTOR pathway." (PMID 30089483, 2018). "In addition, metformin and phenformin trigger the activation of AMP-activated protein kinase (AMPK) that in turn antagonizes the activity of pro-tumor mammalian target of rapamycin (mTOR) signaling, leading to delayed tumor growth and reduced metastasis." (PMID 30337872, 2018). "This would allow pushing autophagic tumor cells, whether constitutively present or induced following mTOR inhibition, toward demise." (PMID 30013478, 2018). "It has been shown that Hsp90 inhibition may subsequently trigger the development of a heat shock response by upregulation of Hsp70, and the latter can be blocked by pre-treatment with mTOR inhibitors, such as cycloheximide in multiple tumor types." (PMID 29594044, 2018). "Although, recent reports implied that niclosamide inhibits tumor growth through suppressing Wnt, Notch, mTOR and STAT3 pathways, its exact antitumor mechanism remains unclear." (PMID 30258081, 2018). "The PI3K/mTOR pathway was again implicated when analysing the expression profiles of PanNETs, with a particularly evident association between low PTEN and TSC2 expression levels and development of metastasis, tumour progression and poor overall survival." (PMID 29321190, 2018). "Published data proved that mTOR was the direct target gene of miR-100 in tumor cells." (PMID 30563983, 2018). "In addition, many in vitro studies have shown that melatonin-rich residue particles can cause tumor growth by modulating cell signaling pathways, such as MEK/ERK and PI3K/Akt/mTOR pathways." (PMID 30249816, 2018). "Apart from the PGK1-induced enhancement of energy supply, the mechanism might involve the stimulation of PGK1-activated oncogenic AKT/mTOR pathway in tumor cells." (PMID 29954422, 2018). "In addition, clinical trials that specifically address the effects of mTOR inhibitors on tumour cachexia are needed." (PMID 30061533, 2018). "The limited effects of both the first and the second generation of mTOR inhibitors on tumor growth could be overcome by using a combined treatment." (PMID 29772672, 2018). "IHC was performed to determine the expression of mTOR in the tumours." (PMID 29266795, 2018). "Conversely, oncogenes, including Akt, mTOR and Bcl-2, inhibit autophagic processes indicating that elevated autophagy signaling may contribute to tumor suppression." (PMID 29329543, 2018). "Taken together, these data revealed that COE could further promote tumor cell apoptosis when mTOR signaling pathways are suppressed." (PMID 30526568, 2018). "The mTOR pathway is essential for tumor cell growth, proliferation and survival." (PMID 29554968, 2018).
tumor (continued). "Another process through which exercise might regulate tumor metabolism is the autophagic machinery, as described in Autophagy and mTOR Signaling." (PMID 30363988, 2018). "Hence, it seems highly probable that mTOR inactivation sensitized the tumor to crizotinib by suppressing mTOR triggered bypass signaling." (PMID 29755689, 2018). "This evidence confirms that DANCR may play a tumour suppressor role by sponging miR‐496, which in turn affects its target, mTOR." (PMID 29266795, 2018). "Studies in vitro suggest FLCN has a role facilitating mTOR activation at the lysosome surface, however further studies are needed to clarify mechanisms involved in mTOR signalling by the FLCN/FNIP complex and possibly validate the role of mTOR inhibition in tumour progression suppression." (PMID 30326848, 2018). "At the same time, ApoE could activate PI3K/AKT/mTOR signaling pathway, which has been confirmed as a critical regulator during tumor progression, including cell–cell adhesion, proliferation, and migration." (PMID 30631342, 2018). "Glutaminolysis in tumor cells is critical to replenish metabolites by anaplerotic reactions, which could result in competition between tumor cells and TILs for glutamine that controls mTOR activation in T cells and macrophages." (PMID 29482595, 2018). "Together, our results demonstrate how UBTOR regulates cell growth and neoplasia via mTOR signaling." (PMID 30080879, 2018). "The RTK pathway and the TSC/mTOR pathway showed high cross-signaling across most major tumor types." (PMID 30297783, 2018). "Based on the concepts of innate and adaptive resistance, PD-L1 might be a convergence point for the IFN pathways and the Akt/mTOR pathway, and these pathways may create a vicious cycle in the tumor microenvironment of RCC patients." (PMID 29423114, 2018). "Furthermore, negative regulation of mTOR by two Tuberous Sclerosis complexes (TSC1-2) was found to result in tumor suppression." (PMID 30138330, 2018). "Although accumulating evidence suggests that mTOR signaling may play a role in this scenario, our understanding on the biological roles and therapeutic implications of tumor-intrinsic PD-1 remain very limited." (PMID 30105035, 2018). "Taken together, these results show that patients treated with mTOR inhibitors present more frequently signs and symptoms that are either part of tumour cachexia or specific to mTOR inhibitors and in this case, that may worsen cachexia." (PMID 30061533, 2018). "Indeed, we observed activated AKT/mTOR signaling in the graft tumor (indicated by phosphorylated AKT, S6K, RPS6)." (PMID 29755689, 2018). "Furthermore, PSMD7 downregulation contributed to decelerated tumor growth, inhibition of proteasomal function, induced cell apoptosis and attenuated activity of mTOR/p70S6K pathway in vivo." (PMID 29632807, 2018). "It is well documented that one of the key targets of metformin is adenosine monophosphate-activated protein kinase (AMPK), which inhibits the mammalian target of rapamycin (mTOR) and therefore suppresses cell proliferation, induces apoptosis and upregulates tumour suppressor genes and proteins." (PMID 29665787, 2018). "Thus, a prime challenge is to dissect the role of mTOR in the different cell types in the tumor microenvironment and to assess the overall “net effect” of mTOR blockade." (PMID 29662490, 2018). "In conclusion, it was demonstrated that tumor-secreted factors could induce IL-1β maturation via the glucose-mediated signal activation of both NF-κB and mTOR in macrophages in the tumor microenvironment." (PMID 30586442, 2018). "Furthermore, genes involved in cyclin D, mTOR, and Ras signaling were downregulated following MYC knockdown, suggesting that MYC expression was closely associated with tumor cell growth." (PMID 30524948, 2018).
tumor (continued). "Moreover, some breast cancer tumor cells have been shown to be able to recruit MDSC via the mTOR pathway and the production of granulocyte colony-stimulating factor (G-CSF), which in turn promotes tumor progression and metastasis." (PMID 29439457, 2018). "The combination of FGFR inhibitors with agents targeting AKT/mTOR signaling pathway increases the anti-tumor effects induced by FGFR inhibition; this drug combination could represent a new therapeutic strategy for FGFR1-amplified LSQCCs." (PMID 30060526, 2018). "mTOR signaling is also on the receiving end of cues coming from the tumor microenvironment." (PMID 29662490, 2018). "Since we observed, in our tumor samples, that PTCs harboring the BRAFV600E mutation presented higher levels of phospho-AKT Ser473, we were also interested in the effect of the BRAFV600E mutation in the activation status of each mTOR complex." (PMID 29757257, 2018). "Indeed, VPA has been reported to revert epithelial-mesenchymal-transition of mTOR inhibitor resistant tumor cells by targeting histone deacetylases." (PMID 30200497, 2018). "Additionally, we showed that EpCAM-regulated tumour development and treatment sensitivity is associated with activation of the PI3K/Akt/mTOR pathway." (PMID 30419852, 2018). "Lastly, UBTOR depletion promotes tumor growth and mTOR signaling in a xenograft mouse model." (PMID 30080879, 2018). "Treatment of tumor bearing rats with melatonin for 60 days resulted in reduction in tumor size associated with decreased levels of mTOR compared with the negative control." (PMID 29495398, 2018). "It is reported that GOLPH3 can promote tumor growth via activating mTOR signaling pathway." (PMID 29914442, 2018). "In addition, research has also shown that PI3K/mTOR signaling pathway can promote the occurrence of cancer by promoting angiogenesis, accelerating cell growth cycle and promoting tumor cell metastasis." (PMID 29954109, 2018). "These processes sustain that the dysregulation of DDIT4 degradation could be a common event that elevates mTOR signaling during tumor development." (PMID 29707520, 2018). "The PI3K/AKT/mTOR signaling pathway and abnormal activation of this pathway reportedly play an essential role in the progression, metastasis, and chemoresistance of numerous tumor types." (PMID 30423811, 2018). "Therefore, suppression of cytokine production by targeting mTOR represents a treatment strategy to ameliorate tumour cachexia." (PMID 30061533, 2018). "However, once patients stopped taking rapamycin, their lung function began to deteriorate, or the AML tumor recurred due to the transient binding/inhibitory effects of rapamycin towards mTOR complex." (PMID 30050412, 2018). "Tumor cells and T cells compete for nutrient such as glucose in tumor microenvironment, and predominant glucose consumption by tumors metabolically restricts T cell functions (e.g., reduction of mTOR activity/glycolytic capacity/IFN-γ production)." (PMID 30687086, 2018). "PI3K/Akt/mTOR kinases have been reported to regulate tumor initiation and metastasis." (PMID 30004418, 2018). "Inhibition of mTOR has been shown to reverse the mesenchymal phenotype of tumor cells." (PMID 30013478, 2018). "This suggests that LAT1 could be used to modulate mTORC1 in a tumor-specific manner, potentially avoiding the side effects of systemic mTOR inhibition." (PMID 30241549, 2018). "Notably, AKT is regarded as a “Warburg kinase,” and mTOR links tumor cell metabolism and oncogenic signaling." (PMID 29854071, 2018). "MiR-223 may have a tumor suppressor function in OS through the PI3K/Akt/mTOR pathway and could be used in anticancer therapies in OS81." (PMID 29991755, 2018). "In addition to MAPK signaling, mTOR kinase signaling activation is important for tumor cell proliferation and senescence induction." (PMID 29625565, 2018). "Therefore, constitutive activation of the PI3K/Akt/mTOR pathway impedes tumor cell killing and constitutes therapy resistance." (PMID 29515122, 2018).